FAM240C (family with sequence similarity 240 member C)
Gene: Protein-coding gene on chromosome 2 (241,893,988 to 241,902,551, reverse strand). Ensembl gene ENSG00000216921.
Subcellular location (Human Protein Atlas): Nucleoplasm
Genetic constraint (gnomAD): Loss-of-function variants: 14 observed, 9.42 expected, observed/expected ratio (o/e) 1.49, 90% interval 0.96 to 1.92. That is too few expected variants to judge how well the gene tolerates losing a copy. Missense variants: 150 observed, 122.08 expected, observed/expected ratio (o/e) 1.23, 90% interval 1.08 to 1.41. Synonymous variants: 48 observed, 43.74 expected, observed/expected ratio (o/e) 1.1, 90% interval 0.87 to 1.4.
Homologues: Orthologues: macaque FAM240C (93% identical), chimpanzee FAM240C (92% identical).